IL6 (interleukin 6)
Diseases named in the same sentence as IL6 in open-access papers (continued):
Sharing a sentence is not in itself a finding about the gene and the disease.
tumor (continued). "The abscopal effects have been attributed to the induced inflammatory cytokines such as IL-1β, IL-6, and TNF-α released from the primary tumor site or non-tumor cells such as endothelial cells and cancer associated fibroblasts." (PMID 28977985, 2017). "In summary, APS induces the expressions of mRNAs and proteins of TLR4, TRAF-6, NF-κB and AP-1, as well as increasing the levels of TNF-α and IL-6 in the serum of the TLR4+/+ tumor-bearing mice, but not TLR4−/− tumor-bearing mice." (PMID 28303957, 2017). "IL-6, similarly to TNF-α, facilitates tumor development, promoting the conversion of noncancerous cells in tumor stem cells." (PMID 28785138, 2017). "Thus, inhibiting inflammatory response to reduce the production of cytokines such as G-CSF and IL-6, or blocking the ligands for TLR2/4, when the increased CTC counts is detected, might be very important for designing the therapeutic strategy to prevent tumor metastasis." (PMID 28415700, 2017). "OC-expanded NK cells from tumor-bearing mice secreted significantly higher IFN-γ, lower IL-10, and slightly lower IL-6 when compared to the control mice without tumor." (PMID 28424683, 2017). "Our finding on the increase of serum TNFα and IL-6, but not IL-1β, in LLC tumor-bearing mice is similar to these patient data." (PMID 28536426, 2017). "The expression of S100A9 in monocytes exerts a tumour-promoting effect upon co-culture with oral cancer cells, in particular by releasing IL-6 and the activation of NF-κB or STAT-3 that is not achieved in tumour cell monoculture." (PMID 28381274, 2017). "We further found an increase in regulatory cytokines including Il10 and Arg1, but not pro-inflammatory cytokines such as Il6, Tnfa and Il12 in DIO tumours compared with normal tumours using purified CD11b+ myeloid cells." (PMID 27708283, 2016). "We established tumour self-seeding models with or without shRNA or inhibitor treatment and found that both IL-6 shRNA and cryptotanshinone inhibited the seeding of RFP-labelled CTCs into primary tumours." (PMID 26623559, 2016). "We examined expression of VEGF and IL-6 through immunostaining of MDA-MB-231 tumor xenografts, and did not detect any significant changes in VEGF or IL-6 expression." (PMID 27283985, 2016). "However, gemcitabine could not prevent STAT3 phosphorylation in IL-6-treated tumor cell lines." (PMID 27687804, 2016). "We have shown that CHEK2 inhibits the procarcinogenic effects of breast stromal fibroblasts and has a non-cell-autonomous tumor suppressive function through repressing the expression/secretion of SDF-1 and IL-6." (PMID 27484185, 2016). "Inflammatory cytokines, such as IL-6 and TNF-α, are produced by tumours and by nonfat cells residing in AT in addition to adipocytes." (PMID 26508820, 2015). "Composite results show that daily oral intake of mushroom beta-glucan in tumor-bearing mice can lower the amounts of M-CSF gene expression in the lungs but does not affect the amounts of IL-12, GM-CSF, IFN-γ, IL-6, IL-10, COX-2, and TGF-β in the lungs." (PMID 26167490, 2015). "We did not measure levels of IL-6, IL-8, or VEGF, but we expect that they would be similarly decreased in tumor treated cells." (PMID 25836370, 2015). "The levels of cytokines and chemokines, including IL-1β, IL-6, GM-CSF, G-CSF, MCP-1 and TNF-α, were much higher in tumour tissue lysates than in non-tumour tissue." (PMID 26581194, 2015). "IL1RN inhibits PGE2, IL-6 production and MM cell growth, FTH1 is a favorable prognostic protein but is not really known to contribute to anti-tumor response and the death receptor FAS induces apoptosis in a large number of cell types." (PMID 26036313, 2015). "The expression pattern of all the factors (IL-6, IL-6R, gp130, and CD68) was not similar among the tumor tissues, such that all the factors were gradually up-regulated until five weeks." (PMID 26525581, 2015).
tumor (continued). "Take together, our findings clearly demonstrate serum IL-6 rather than IL-27, TNF-α, and VEGF playing a definite role in liver deterioration and tumor progression, as well as further affecting HCC patient survival." (PMID 25908103, 2015). "Activation of the IL6/NF-κB signaling pathway in non-transformed MCF10A cells induces the EMT, a driver of tumor growth and metastasis." (PMID 26536657, 2015). "Serum IL-6, through p-STAT3 rather than p-STAT1 signal pathway, affected hepatic function, tumor progression, and determine HCC patient survival." (PMID 25908103, 2015). "It therefore seems that increased IL-6 levels are a negative prognostic factor in HNSCC patients, although to what extent this is affected by the HPV infection in the tumor is not known." (PMID 26079381, 2015). "Importantly, leptin induces the expression of inflammatory cytokines like IL-1 in tumor cells and non-tumor cells of the tumor stroma; however we were not able to demonstrate IL-1 upregulation by leptin in macrophages, although IL-1 is a major inducer of IL-6 in a variety of cells." (PMID 25599228, 2015). "Le-SC-ASC did not up regulate expression of MCP-1, MIP-2 and IL-6, unlike obese and visceral derived ASC, and in response to tumor secreted factors." (PMID 26317219, 2015). "We found minimal detection of pro-inflammatory cytokines in the serum of the NT group (normal mice without tumor), whereas, tumor bearing mice had significantly elevated levels of TNF-α, IL-6 and IL-1β." (PMID 24885825, 2014). "IL-6 and IL-8 (gray arrows) together with IL-16, IL-17, and IL-17E (white filled arrows) expression profiles differentiated HPV positive and negative tumor cells in vivo." (PMID 25400927, 2014). "The observed upregulation of IL6 and IL8 and downregulation of IL12A were therefore probably due to tumour-specific immunological responses that were independent of the presence of HPV." (PMID 23570247, 2013). "Our data demonstrate that the OSM receptor (OSMR), but not IL-6 or its receptor, is expressed by all human and canine OSA cell lines and canine OSA tumor samples; additionally, OSM expression was noted in all tumor samples." (PMID 21481226, 2011). "Ligands for CCR4 (e.g., CCL17 and/or CCL22) were in contrast to IL-6 and TGF-β not highly expressed in the tumor tissue, altogether indicating a conversion from CD8+ Tconvs rather than a tumor directed migration as the cause for the observed infiltration." (PMID 24212779, 2011). "Given the apparent lack of IL-6/IL-6R expression in the OSA cells, we focused on OSM and its receptor in the fresh frozen OSA tumor samples from canine patients." (PMID 21481226, 2011). "As IL-6 is correlated with both Gleason grade of the individual cores and distant metastasis in our patient cohort, regardless of the Gleason score of the tumours, IL-6 might be one factor that could explain the partial rescue of the Id-1-induced phenotypes by recombinant TNF-β." (PMID 20010941, 2010). "We observed a strong correlation between the increased expression of IL-6 and TLR-4 with increasing tissue dysplasia up to malignancy, higher TLR-4 and IL-6 was also found in tumor tissues derived from animals lacking Tir8 as compared to wild-type controls." (PMID 21059221, 2010). "Although IL-6 and CRP levels were not correlated with other pathological findings, VEGF level was significantly correlated with tumor size (p = 0.012) and CEA (p = 0.038)." (PMID 20465852, 2010). "Finally, we could not ignore the essential impact of tumour environment on cell survival and growth and could imagine that IL-6 inhibition through the use of anti-IL-6 antibodies could block cytokine pools secreted by the neighboring cells and thus could reveal a potent benefit in vivo." (PMID 19956602, 2009). "In extraosseous tumours, cells in contact with malignant cells did not expressed DKK1, MCSF, cathepsin K and IL6." (PMID 18253114, 2008).
tumor (continued). "Both models exhibited the same immunohistochemical labelling pattern: tumour cells never exhibited significant labelling for M-CSF, Dkk-1, RANKL, IL-6 or cathepsin K." (PMID 18253114, 2008). "IL-2 and IL-13 were not correlated with PR status, whereas IL-1β, IL-6, IL-8, IL-10, IFN-γ, MCP-1, MIP-1β, TNF-α and, to a lesser extent, IL-4, IL-12 and G-CSF were more abundant in PR-negative tumours than in PR-positive ones." (PMID 17261184, 2007). "mRNA expression of interleukin (IL)-1 alpha, IL-6, IL-8, interferon (IFN)-gamma, and tumour necrosis factor (TNF)-alpha was observed in untreated tumour tissues, which were not enhanced by cyclophosphamide treatment." (PMID 8688335, 1996). "Interestingly, a significant correlation was found between the expression of TGF-β and IL-6 expression in primary CRC tumor and FN1 in the metastatic intrahepatic tumor but not the local primary CRC tumor." (PMID 40335453, 2025). "In this tumor context, AMP did not directly inhibit tumor-cell proliferation but activated BMDMs, enhancing their phagocytic and migratory activity and increasing the production of TNF-α, IL-6, IFN-λ in BMDMs and in the serum of tumor-bearing mice." (PMID 41374013, 2025). "However, IL-6 and CXCL9, baseline concentrations did not significantly differ by patient age group when evaluating within the same tumor type (P > 0.05)." (PMID 40258833, 2025). "Notably, cerebrospinal fluid and peripheral blood monocytes are major sources of IL-6, IL-18 (a chemokine subclass), and TNF-α (which selectively targets tumor cells without significant toxicity to normal cells)." (PMID 41458177, 2025). "qPCR analysis of the tumor tissue indicated that the presence of CAF during tumorigenesis upregulated the expression of CXCL5, whereas the expression of CXCL1, 2, 3, 6, 7, 8, and IL-6 were not significantly affected." (PMID 41392310, 2025). "Intriguingly, in CRC, macrophages amplify IL-6 production from cancer cells themselves, suggesting that a substantial portion of IL-6 present in CRC’s TME might primarily be derived from the tumor cells rather than the macrophages." (PMID 39286635, 2024). "The results of the P815-IFNG tumor models displayed a significant increase in the transcriptional or translational levels of murine IFNG and CXCL10 in the light group, rather than IL-6 or IL-10." (PMID 39080467, 2024). "Moreover, presurgical serum IL-6 levels greater than 10 pg/mL are predictive of diminished survival in patients with CRC, independent of the tumor site, grade, and stage." (PMID 39451248, 2024). "The increased Treg infiltration of the tumor was independent of TGFβ signaling, suggesting a systemic distribution of CXCL8 and IL6 produced by cancer cells, which results in increased neutrophil production, Foxp3 upregulation on T lymphocytes, and tumor trafficking through CXCR1." (PMID 39409924, 2024). "At the same time, loss of NF1, TSC1, or TβRII promoted the production of soluble inflammatory mediators such as IL6 and IDO1, which resulted in a non-cell-autonomous immune-suppressive tumor microenvironment that is characterized by increased LAG3+ CD8 and CD4 T cells." (PMID 38997291, 2024). "Thus, 10 μM was chosen as a non-toxic concentration to study the effects of HIS on the IL-6/STAT3/S100A9 pathway, excluding direct tumor growth interference." (PMID 39720595, 2024). "Although we identified many similarities between the previously identified tumour promoting cytokine network and cytokine signalling in the MES subtype, IL6 in specific was neither observed in the ligand–receptor analysis nor significantly differentially expressed compared to the other subtypes." (PMID 37370765, 2023). "Some cytokines in TME, such as macrophage colony stimulating factor, IL-4, IL-6, IL-10, TGF-β and VEGF can alter the differentiation of DCs and inhibit the activation and maturation of DCs, resulting in a lack of mature and functional DCs in tumor patients." (PMID 37064113, 2023).
tumor (continued). "Interestingly, we found that blocking CCL18, but not IL-6 and IL-8, significantly inhibited the upregulation of CD10 and GPR77 in NBFs exposed to chemoresistant tumor CM." (PMID 36418470, 2023). "Furthermore, the co-cultures with CD19-negative K562 tumor cells did not lead to activation of CAR T cells and hence did not stimulate monocytes to release IL-6." (PMID 37947658, 2023). "Interestingly, treatment of the “negative” tumor cells with WGA or MAA triggered an increase in IL1β, IL6, IL8 and/or MIP1β secretion(lines with negative impact in red)." (PMID 36891308, 2023). "TLR4, IL-6 and TNF-α expression was upregulated by palmitic acid in a neuroblastoma cell line in vitro and in vivo, TLR4-/- colorectal cancer (CRC) tumor growth was not affected by a diet enriched with palmitic acid, while wild-type CRC tumor growth was increased upon dietary intervention in mice." (PMID 36830818, 2023). "Interestingly, the TCM from the poorly immunogenic tumor CT26 and recombinant IL6 alone did not modulate CCL3 or CCL4 production." (PMID 35064009, 2022). "In conclusion, we show that in the absence of STAT3, IL-6 induced prolonged STAT1 signaling and expression of STAT1 target genes, which suggests an interplay of STAT1 and STAT3 signaling in the presence of proinflammatory IL-6 in the tumor microenvironment." (PMID 35267462, 2022). "Here, baseline HSV was the only parameter (p=0.045) that significantly predicted IL-6 levels, whereas BMI (p=0.334), ECOG (p=0.448), smoking (p=0.728), T stage (p=0.583), N stage (p=0.880), HPV status (p=0.708), tumor volume (p=0.137), and [18F]FMISO T/M ratio (p=0.651) had no significant impact." (PMID 34773163, 2022). "However, only STINGR284S mRNA, not STINGWT mRNA, stimulated the production of anti-tumor cytokines, such as CCL5, CXCL10, IL29, IL6, IFNβ and TNFα." (PMID 36498833, 2022). "Also, IL-6, TNF-α and IL-12P7 levels did not correlate with age, gender, tumor site and histological classification (P> 0.05)." (PMID 36226059, 2022). "Even in the absence of tumor cells, chemotherapeutic agents can transform fibroblasts into a CAF-like senescent phenotype which produce pro-tumor inflammatory cytokines, including IFN and IL-6." (PMID 34439387, 2021). "Interestingly, we observed that although the serum levels of several cytokines including IL‐6, TNF‐α, and IL‐1β (but not IL‐1α) increased in C26‐tumor‐bearing mice, these effects were prevented by treatment with GW (Fig EV3, EV4D–G)." (PMID 34096686, 2021). "However, only KPC cells (left) were positive for IL-6, while KPC IL6KO tumor cells showed no immunoreactivity (right)." (PMID 33851955, 2021). "After eradication of tumor targets, macrophages and monocytes were still active in secreting IL6, but CART-secreted anti-IL6 blocker decreased significantly and could not efficiently neutralize the high level of IL6 after CRS ended." (PMID 33907185, 2021). "Moreover, although it did not significantly affect the level of TNF‐α and IL‐6 in liver tissues, S3I‐201 obviously restrained the enhanced STAT3 activation and EMT change of tumour tissues in the liver injury group." (PMID 33410581, 2021). "However, treatment with several cytokines, including IFN-γ, IL-2, IL-4, and IL-6, did not raise VISTA expression in tumor cells." (PMID 34728682, 2021). "Here, tumor cells together with non-malignant stromal cells trigger CAF activation through inflammatory mediators such as transforming growth factor beta (TGF-β), interleukin (IL)-1, and interleukin (IL)-6 that contribute to inflammation and carcinogenesis." (PMID 34830058, 2021). "Moreover, there were no marked differences in gene expression of key tumor cell division (p27, CDK4 and Hes1) and inflammation markers (F4/80 and IL-6) following metformin treatment." (PMID 34829914, 2021).
tumor (continued). "NHE-06 administration decreased IL-6 levels and downregulated IL-1β and COX-2 expression in mice bearing subcutaneous Hepa1-6 tumors, which is indicative of inactivated NF-κB/IL-6/STAT3 signaling and restored tumor immunity without direct tumor cytotoxicity." (PMID 32595757, 2020). "Importantly, the blockade of TNF resulted in an improvement of tumor survival in DSS-treated tumor-bearing mice after ICB therapy, unlike IL-6 neutralization, which harmed rather than improved ICB-enhanced anti-tumor responses." (PMID 31309173, 2019). "Neutrophil IL6 and IL10 expression were not altered by the tumor." (PMID 31712726, 2019). "Interestingly, we also found that myofibroblasts did not induce IL‐6 in response to TGFβ or IL‐1, supporting that this CAF population is tumor suppressive." (PMID 31609088, 2019). "Irg1 induction was still observed when TNF-, IFN-γ-, IL-6-, or TLR4-KO mice were inoculated with tumors, however, we could not rule out the possibility that tumor-derived cytokines influence pResMφ." (PMID 29920191, 2018). "In accordance with the high-tumor burden setting, the antitumor effects of all three NGFR isoform-enriched CD44v6 CAR-T cells were accompanied by elevated systemic levels of human IFN-γ, in the absence of IL-6 and IL-10." (PMID 29619024, 2018). "Following (+)-JQ1 treatment, IL6 and PTHrP expression is reduced in tumors derived from C26 cells, suggesting that (+)-JQ1 modifies the tumor transcriptional program and prevents pro-cachectic factors upregulation, without affecting tumor mass." (PMID 29167426, 2017). "On the other hand, the basal-like MDA-MB-231 cells, whose aggressiveness-related features depend on IL6 and IL8 secretion, almost completely lack mammosphere formation and differentiation capacities, suggesting that tumour aggressiveness is not always related to stemness." (PMID 28472950, 2017). "However, following stimulation with α-c-myc tag monoclonal antibody or the tumor cells 24JKERB, we detected a range of cytokines, including IL-4, IL-2, IL-17A, TNF-α, IL-6 and IFN-γ from CAR T cells, while no significant response was observed from WT T cells." (PMID 27153556, 2016). "While alterations in tumor distribution could affect circulating cytokines, PDTC treatment did not alter the induction of plasma IL-6 in ApcMin/+ mice." (PMID 27449092, 2016). "However, neither STAT3 activation nor anti-tumor activity of IL-6 antibody CNTO328 was observed in our HCC4006ER cells, suggesting that the IL-6/STAT3 pathway is not necessarily activated in EMT-related acquired EGFR-TKI resistance in NSCLC." (PMID 26789630, 2016). "Quantitative real-time PCR analysis of total tumor mRNA confirmed an increase of PD-1 transcript levels but not PD-L1 levels or inflammatory cytokines such as tumor necrosis factor α (TNF α) and interleukin-6 (IL-6)." (PMID 27129180, 2016). "Likewise, chemokines and cytokines are extensively produced in the tumor microenvironment regardless of the initial triggers, and mediators such as IL-1β, TNFα, CCL2 and IL-6 directly promote tumor progression in experimental models of CRC." (PMID 27494857, 2016). "Two recent reports show that both IL-6-Stat3 and HGF-Met oncogenic signaling pathways are negatively regulated by miR-26a in HCCs, suggesting that downregulation of miR-26a promotes proliferation, migration and invasion of tumor cells in vitro and in vivo." (PMID 25537511, 2015). "Conversely, mRNA levels of VEGF, MIP-2, TGF-β1, IL-6, and IL-8 were all significantly up-regulated in GCN-MSCs or BM-MSCs after 10 % BGC-823-CM or MKN-28-CM treatment, suggesting a converted progression of non-malignant MSCs by tumor cells." (PMID 25986392, 2015). "Our recent studies suggested that enhanced expression of SOCS3 could reduce tumor metastasis, the expression of epithelial-to-mesenchymal transition (EMT) markers and STAT3 activation in the absence of interleukin-6 (IL-6) stimulation in CCA cell lines." (PMID 26485275, 2015).